WWTR1 (WW domain containing transcription regulator 1)
Diseases named in the same sentence as WWTR1 in open-access papers (continued):
Sharing a sentence is not in itself a finding about the gene and the disease.
tumor (68 papers, 2016 to 2025). "Analysis of clinicopathological characteristics shows that WWTR1 expression is significantly associated with GCA tumor invasion (T stage), lymph node metastasis (N stage), and remote metastasis (TNM stage IV)." (PMID 30976198, 2019). "These clinicopathological data strongly suggest an association of WWTR1 expression with tumor invasion and metastasis in GCA, particularly with remote metastasis as WWTR1 expressed in TNM stage IV tumors with a significantly high frequency (81.8%)." (PMID 30976198, 2019). "We found that WWTR1 expression is positively correlated with tumor invasion and metastasis of GCA and inversely associated with cumulative survival of GCA patients." (PMID 30976198, 2019). "More importantly, expression of WWTR1 significantly associated with tumor invasion and metastasis (in T stage, p = 0.031; N stage, p < 0.01; and TNM stage, p < 0.001)." (PMID 30976198, 2019). "Recently, many roles for Yes-associated protein (YAP) and TAZ (encoded by WWTR1) as main mediators of the Hippo pathway have been described in (a) regulating organ size; (b) promoting tumor initiation, progression, metastasis, and EMT; and (c) reprogramming cancer cells into CSCs." (PMID 33408328, 2021). "For example, WW domain-containing transcription regulator 1 (WWTR1) is a key regulator in the Hippo signaling pathway, which inhibits proliferation and promotes apoptosis to control organ size and tumor suppression." (PMID 39941831, 2025). "Based on the immunohistochemical results, it was considered that the tumor was derived from vascular endothelial cells, supplemented by molecular pathological examination showing WWTR1-CAMTA1 gene fusion." (PMID 40958872, 2025). "Histologically, EHE is a malignant tumor composed of vascular endothelial cells accompanied by a distinctive myxoid-hyaline transformation of the mesenchyme with WWTR1::CAMTA1 and YAP1::TFE3 fusion genes." (PMID 39917171, 2025). "This fusion results in constitutive activation of WWTR1, which promotes abnormal cell proliferation, inhibits tumor cell death via autophagy, and ultimately drives tumor growth and progression." (PMID 40919137, 2025). "Upstream tumor suppressors, including MST1, LATS1/2, and FAT1/2/3/4, frequently undergo deletions or mutations, whereas downstream oncogenes such as YAP1, WWTR1, and TEAD1/2/3/4 are upregulated." (PMID 41256331, 2025). "Select genes including ALDH3B1, CEACAM5, IL8, PYGO2, and WWTR1, exhibited pronounced activity in promoting tumor formation and establishing gene dependencies critical for tumorigenicity." (PMID 38851782, 2024). "The YAP1::TFE3 fusion was identified in one case (#130), and this tumour demonstrated unique morphology compared to tumours harbouring the more common WWTR1::CAMTA1 fusion." (PMID 37686662, 2023). "As expected, we found that the value of 3 PDEARGs (ANXA1, COL6A1, and PDPN) and key DETF (WWTR1) were co‐expressed significantly higher in the tumor core than in the peripheral of GBM tissue, specifically in the neoplastic cells." (PMID 37434432, 2023). "We observed strong focal staining of YAP1 and WWTR1 in a subpopulation of cells within a tumor section that was otherwise positive for H&E and ATOH1 (red arrows)." (PMID 36719743, 2023). "Staining for YAP1 and WWTR1 revealed a few rare cells that were positive within the tumor sections assessed." (PMID 36719743, 2023). "The closely related transcriptional co‐regulator proteins YAP and TAZ (WWTR1) have emerged as important drivers of tumour initiation, progression and metastasis in melanoma and non‐melanoma skin cancers." (PMID 35913427, 2022). "Three tumor samples (T5, T16, and T19) exhibited high-level amplification in 3q26, including WWTR1, TP63, PIK3CA, SOX2, SOX2-OT, and ZNF639 genes." (PMID 34285259, 2021). "The tumor most commonly results from a translocation between chromosomes 1 and 3 that creates a pathopneumonic WWTR1-CAMTA1 fusion protein." (PMID 33194900, 2020).
tumor (continued). "Emerging evidence demonstrate that YAP1 and WWTR1 have distinct roles where they partner with different transcription factors, drive different downstream effectors and also modulate the tumor microenvironment distinctively." (PMID 32990596, 2020). "In this report, we examined expression of WWTR1 in tumor samples from 214 GCA cases using tissue microarray assay (TMA) and statistically analyzed association of WWTR1 expression with cumulative survival of GCA patients and clinicopathological data." (PMID 30976198, 2019). "The expression of a specific module—whose regulators were GAP43 and WWTR1 genes—had been reported to correlate with the necrotic process and with the presence of blurry edge necrotic portion of the tumor." (PMID 31795520, 2019). "It has been observed that WWTR1 activates EMT signaling pathway that promotes tumor growth, migration, and invasion by co-activating TEAD-mediated EMT gene transcription." (PMID 30976198, 2019). "Expression of WWTR1 in both the GCA tumor tissues and the adjacent normal tissues from 214 GCA cases was detected by IHC staining using tissue microarray assay (TMA)." (PMID 30976198, 2019). "Currently, there are several signaling pathways have been proposed involved in WWTR1-promoted tumor metastasis." (PMID 30976198, 2019). "MST1/2 and LATS1/2, upstream regulators of the Hippo tumor-suppressing signaling, are frequently deleted and mutated, whereas the downstream effectors, YAP and WWTR1 (encoding TAZ), are frequently amplified." (PMID 30401982, 2019). "In this list, WWTR1 is known as a downstream regulatory target in the Hippo signaling pathway that plays a key role in tumor suppression." (PMID 30598101, 2018). "Accordingly, the pathway has emerged as a tumor suppressive pathway that acts to control the transcriptional activity of two related proteins, YAP (Yes-associated protein) and WWTR1, also referred to as TAZ4,5." (PMID 30158528, 2018). "Moreover, confirming the presence of WWTR1::CAMTA1 or YAP1::TFE3 gene fusion in the tumor would offer more convincing evidence." (PMID 40040722, 2025). "Aberrant nuclear localization of YAP/TAZ—often driven by high-frequency genomic events such as FAT1 loss, WWTR1 amplification and YAP1 amplification—correlates with increased tumor proliferation, metastasis, chemoresistance and significantly shorter overall and progression-free survival." (PMID 40486910, 2025). "Indeed, loss of CDKN2A in one EHE GEMM was found to cooperate with the WWTR1::CAMTA1 fusion to enhance tumor progression." (PMID 39283723, 2024). "The reciprocal expression pattern between YAP1 and WWTR1 and the cluster 0/NE genes and the correlation with viral status was more evident in the established cell line RNA-Seq data than it was for the PDCLs or 44 tumor biopsies." (PMID 36719743, 2023). "Differences in expression pattern may reflect cell lines derived from subpopulations of YAP1- and WWTR1-expressing cells within the tumor or from culture conditions." (PMID 36719743, 2023). "We asked whether the reciprocal expression of YAP1- and WWTR1-dependent genes and NE markers could be observed in the bulk RNA-Seq of the 44 tumor biopsies." (PMID 36719743, 2023). "Interestingly, transcriptional profiling grouped OFMT cases with different gene fusions, except the case with KDM2A::WWTR1, which clustered with other tumor types." (PMID 36551696, 2022). "In the past decade, increasing evidence has emerged to support the contribution of the dysfunctional Hippo pathway, especially core Hippo signaling effectors yes-associated protein 1 (YAP1) and WW domain-containing transcription regulator 1 (TAZ), in tumor initiation, progression, and recurrence." (PMID 36289774, 2022). "Notably, the TCGA data analysis revealed a significant correlation between WWTR1 gene levels and lymph node infiltration by the tumor, in accordance with our data." (PMID 35655220, 2022).
tumor (continued). "Ultimately our findings both identify a novel tumor-suppressor miRNA, and also characterize previously unknown regulatory pathways governing WWTR1 expression in AML." (PMID 33061801, 2020). "The results have shown that WWTR1 is overexpressed in 66.4% of the GCA tumor samples." (PMID 30976198, 2019). "Recently, a study described the mechanism of action of a WWTR1(TAZ)-CAMTA1 fusion oncoprotein, and the results suggested that the WWTR1-CAMTA1 fusion might cause resistance to anoikis and the oncogenic transformation of tumor cells." (PMID 26840265, 2016). "EHEs have been characterized by tumor-specific WW domain-containing transcription regulator 1(WWTR1)-calmodulin-binding transcription activator 1 (CAMTA1) translocations, and recently, a novel Yes-associated protein 1 (YAP1)-transcription factor E3 (TFE3) gene fusion was identified in EHEs." (PMID 26840265, 2016). "Furthermore, YAP1 and WWTR1 expression inhibits the tumor progression of Merkel cell carcinoma." (PMID 38246995, 2024). "This process involves WWTR1 (TAZ)::CAMTA1 as a continuously activated form of TAZ, which is mainly located in the cell nucleus and activates its pro-tumor transcription program." (PMID 40040722, 2025). "LYRIC is a functional protein that regulates EMT and its activation involves the activation of transcription factors (YAP1 and WWTR1/TAZ) of the Hippo signaling pathway, inducing tumor cell ferroptosis." (PMID 38469234, 2024). "The Hippo pathway transducers yes-associated protein (YAP) and WW-domain containing transcription regulator 1 (WWTR1/TAZ) are key regulators of liver tumorigenesis, promoting tumor formation and progression." (PMID 39126118, 2024). "The top pathway in the non-tumor-specific sex-DMPs of SHH is YAP1- and WWTR1 (TAZ)-stimulated gene expression." (PMID 37035203, 2023). "We compared the transcriptome data between normal samples and GBM tumor samples, which indicated that ANXA1, PDPN, COL6A1, BCL3, RUNX1, and WWTR1 were upregulated and compared to normal samples, BCL11A was downregulated in GBM tumor samples." (PMID 37434432, 2023). "In line with this, expression levels of YAP1 and WWTR1 as well as their target genes CTGF and CYR61 were significantly decreased in ER+ BRCA relative to their non-tumour tissues." (PMID 35217640, 2022). "Yes-associated protein 1 (YAP) and transcriptional coactivator with PDZ-binding motif (WWTR1, TAZ) are mechanoresponsive transcription factors phosphorylated by the active Hippo tumor suppressor pathway." (PMID 35284040, 2022). "The overexpression WWTR1, a transcriptional coactivator with the PDZ-binding motif, leads to tumor proliferation and CSC renewal." (PMID 36231068, 2022). "CAF-derived ANGPTL2, WWTR1, and PLOD2 promote tumor progression and cell invasion, and MYO10 regulates CAF rigidity." (PMID 33917869, 2021). "We now show that SKI also functions independently of SMAD/TGF-β signaling, by activating the Hippo tumor-suppressor pathway and inhibiting the Transcriptional co-Activator with PDZ-binding motif (TAZ or WWTR1)." (PMID 33847835, 2021). "The tumor expresses a fusion gene between FOSB and either SERPINE1, ACTB, or WWTR1, which results in an overexpression of FOSB." (PMID 33194900, 2020). "The PKA-downstream YAP and WW-domain-containing transcription regulator 1 (TAZ) also display oncogenic features in PDAC, through switching off the Hippo tumor suppressor pathway." (PMID 33266496, 2020). "Unlike previous reports which claimed mutually exclusive occurrence of WWTR1-CAMTA1 translocation and YAP1-TFE3 gene fusion, tumor cells from the TFE3-positive EHEs showed separate signals, indicating the presence of CAMTA1 translocations." (PMID 26840265, 2016). "Histopathological examination of the epididymal biopsy showed tumor cells with specific morphological features, and immunohistochemistry (IHC) indicated CD31(+), CD34(+), Fli-1(+), ERG(+), Ki-67(+5%+), along with WWTR1-CAMTA1 gene fusion by fluorescence in situ hybridization (FISH), confirming EHE." (PMID 40978723, 2025).
tumor (continued). "Tumor cells had fusiform and oval nuclei with mild atypia, and intracytoplasmic vacuoles, imparting a signet-ring like appearance, with CAMTA1-immunonegativity but WWTR1::CAMTA1 fusion." (PMID 40040722, 2025). "Here, we characterized the expression profiles of MCC tumor biopsies, PDCLs, and established cell lines to identify a spectrum of NE gene expression that is negatively correlated with the expression of YAP1 and WWTR1." (PMID 36719743, 2023). "Furthermore, we also found KRT8, a marker of normal Merkel cells and MCC, coexpressed in single cells with higher levels of WWTR1 (center) indicating that these WWTR1-expressing cells probably represented MCC tumor cells." (PMID 36719743, 2023). "While both cases #521 and #368 also had the common EHE fusion gene WWTR1::CAMTA1, these additional molecular features may indicate a more aggressive tumour phenotype." (PMID 37686662, 2023). "WWTR1 (also known as TAZ) and YAP1 as the major downstream effectors of the Hippo pathway are found not only to trigger numerous cell‐autonomous responses, but also to participate in choreographing tumour‐stromal interactions." (PMID 33660944, 2021). "So, NRF2 has been identified as one such mechanism, hence probably counteracting repressor signals and providing a tumor growth advantage, concluding that an efficient therapy for GBM must consider that high NFR2 and WWTR1 levels are predictors of chemoresistance." (PMID 34948224, 2021). "The average IHC staining score of WWTR1 in the GCA tumor tissue is 94.67 ± 74.82 while in the normal tissue is 70.84 ± 57.04 (p = 0.0002), indicating that expression of WWTR1 is significantly higher in the tumor tissue than in the normal tissue." (PMID 30976198, 2019). "In addition, staining of WWTR1 in GCA tumor cells was distributed all over the cell, no specified cellular localization was seen." (PMID 30976198, 2019).
infection (2 papers, 2020 to 2022). The state of being infected such as from the introduction of a foreign agent such as serum, vaccine, antigenic substance or organism. "After 2 h of infection, the transcriptional upstream regulators EGFR, EGR1, FOXL2, FOXO3, IL1A, IL1B and RELA were activated in MKN-28 cells infected with either H. pylori wt or the ΔhtrA mutant, while WWTR1 was inhibited." (PMID 37193047, 2022).
WWTR1 also shares sentences with these, for which no sentence is quoted: liver cancer (3 papers); Poroma (3); embryonal rhabdomyosarcoma (2); endometrial stromal sarcomas (2); epithelioid sarcoma (2); renal cell carcinoma (2); soft part sarcoma (2); alveolar soft part sarcoma (1); anaplastic cancer (1); anaplastic thyroid cancer (1); Barrett esophagus (1); Bartonella infection (1); blood cancers (1); Camurati-Engelmann disease (1); cervical squamous cell carcinoma (1); cholangiocarcinoma (1); clear cell sarcoma (1); coloboma (1); colon cancer (1); esophageal squamous cell carcinoma (1); Ewing sarcoma (1); Fibrolamellar carcinoma (1); fibromyxoid tumor (1); hemangioma (1); hepatocholangiocarcinoma (1); inflammatory myofibroblastic tumor (1); intrahepatic cholangiocarcinoma (1); intrauterine growth restriction (1); kidney cancer (1); liver cirrhosis (1).
A further 14 diseases each share a sentence with WWTR1 in 1 paper.